FH (fumarate hydratase)
Diseases named in the same sentence as FH in open-access papers (continued):
Sharing a sentence is not in itself a finding about the gene and the disease.
age-related macular degeneration (9 papers, 2012 to 2025). Age-related loss of vision in the central portion of the retina (macula), secondary to retinal degeneration. "The rational for this is that H402 in human FH is a strong risk factor for age-related macular degeneration and other human pathologies, but the functional consequences of changing Tyr for His at this position are still under debate." (PMID 39944688, 2025). "Genetic variants in the CFH and CFI genes that lead to haploinsufficiency (i.e., ~50% reductions in the levels of FH and FI) have been associated with age-related macular degeneration (AMD)." (PMID 32064578, 2020). "There is a polymorphism Y402H in the human FH gene, where the H variant predisposes individuals to age-related macular degeneration." (PMID 30779817, 2019). "Mutations and polymorphisms in fH are most commonly associated with atypical hemolytic uremic syndrome (aHUS) and age-related macular degeneration (AMD), however links to SLE and glomerulonephritis are also reported." (PMID 33562189, 2021). "Mutations or polymorphisms of fH are associated with the pathogenesis of various inflammatory human diseases, for instance atypical hemolytic uremic syndrome (aHUS) and age-related macular degeneration (AMD) due to dysregulation of the AP." (PMID 30619374, 2018). "The functional consequences and relevance to disease progression of this remain to be ascertained; however, in age-related macular degeneration (AMD), differential binding of the fH-Tyr402His variants in retina has been demonstrated and proposed as the mechanism by which fH-His402 is risk for AMD." (PMID 24887075, 2014). "For example, in age-related macular degeneration (AMD), a retinal disease clinically and pathologically linked to LOAD, genes encoding complement components C2, C3, FB and C9, and regulators FH and FHR4, all contribute to risk." (PMID 33804666, 2021). "FH mutations are associated with severe human renal and retinal diseases, including atypical hemolytic uremic syndrome (aHUS), membranoproliferative glomerulonephritis II (MPGN II), or age-related macular degeneration (AMD)." (PMID 38540259, 2024).
Encephalopathy (9 papers, 2008 to 2024). Encephalopathy is a term that means brain disease, damage, or malfunction. "Moreover, it was shown that FH deficiency could lead to metabolic disorder with severe encephalopathy, seizures, and poor neurological outcomes." (PMID 27556703, 2016). "Deficiencies of FH and SDH(A) generally result in early-onset, severe encephalopathy." (PMID 18366737, 2008). "Finally, patients with inherited deficiencies in TCA enzymes such as fumarate hydratase (FH) and α-ketoglutarate dehydrogenase (α-KGDH) present, among other symptoms, progressive and severe encephalopathy, psychiatric and pyramidal symptoms, and developmental delay." (PMID 38474374, 2024). "In addition, FH deficiency also could lead to metabolic disorders with severe encephalopathy, seizures and poor neurological outcome, suggesting an important role of FH in neurology as well." (PMID 27556703, 2016).
pancreatic cancer (9 papers, 2009 to 2024). "One patient that also had FH(+), with only one affected relative (third-degree with pancreatic cancer), presented BC as only tumor (diagnosed at 25 years of age), and carried a LPV in SLX4 gene (c.4881del, p.Thr1628fs)." (PMID 36329109, 2022). "The increase in FH O-GlcNAcylation promotes development of pancreatic tumors." (PMID 30271380, 2018). "Consequently, the decrease of FH phosphorylation correlates with elevated protein O-GlcNAcylation and poor prognosis in pancreatic cancer patients." (PMID 30271380, 2018). "Moreover, pancreatic cancer cells significantly increased expression of MCT1 (monocarboxylate transporter 1), FH (fumarate hydratase), and SDH (succinate dehydrogenase), showing the existence of metabolic cooperation between CAFs and cancer cells." (PMID 32015297, 2020). "Other antigens such as EF-Tu, HSP70, HSP60, aldolase, fumarate hydratase, aldose reductase, aconitase, HnRNP1, EF-TU, VCP and enolase have been reported for other cancers including cutaneous T cell lymphoma, and renal, hepatic, lung and pancreatic cancers but not for melanoma." (PMID 19381273, 2009).
papillary renal cell carcinoma (9 papers, 2014 to 2025). A rare subtype of renal cell carcinoma, arising from the renal tubular epithelium and showing a papillary growth pattern, which typically manifests with hematuria, flank pain, palpable abdominal mass or nonspecific symptoms, such as fatigue, weight loss or fever. "Fumarate hydratase, which is deactivated in papillary renal cell carcinoma, is responsible for the hydration of fumaric acid to malic acid, which is a part of the Krebs cycle." (PMID 35967759, 2022).
melanoma (8 papers, 2009 to 2025). A malignant, usually aggressive tumor composed of atypical, neoplastic melanocytes. "We first looked at an extended list of high-risk genes predisposing to melanoma (ACD, CDKN2A, CDK4, POT1, TERF2IP, and TERT) or RCC (CDKN2B, FH, FLCN, MET, PBRM1, PTEN, SDHs, TSCs, and VHL) or both (BAP1 and MITF)." (PMID 34067022, 2021). "Previously unreported, fumarate hydratase, which converts fumarate to malate, driving the TCA cycle, was reduced in CREB overexpressing, while significantly increased in CREBS133A mutated A375 melanoma cells." (PMID 41258756, 2025). "In addition, overexpression of a TCA‐promoting gene, fumarate hydratase (FH), in CREB overexpressing melanoma cells (CREBTG/FH), resulted in an impressive reduction in melanoma size in comparison to melanomas that developed after injection of CREBTG A375 melanoma cells." (PMID 41258756, 2025). "In contrast, none of the 7 participants with FH or FLCN mutations were reported to have clinical indicators of HLRCC or BHD syndrome and none of the 10 carriers of P MITF variants had a past history of melanoma." (PMID 35441217, 2022).
renal medullary carcinoma (8 papers, 2019 to 2026). "Histologically, collecting duct carcinoma is a diagnosis that requires diligent exclusion from another epithelial tumor, urothelial carcinoma, SMARCB1-deficient renal medullary carcinoma (RMC), FH-deficient RCC, and high-grade RCC and is vanishingly rare." (PMID 40361453, 2025). "As for the remaining patients, 5/31 had papillary RCC, 2/31 had renal medullary carcinoma (RMC), 2/31 had clear‐cell RCC, and 1/31 had fumarate hydratase (FH) deficient RCC." (PMID 39102694, 2023). "The following entities should be always be considered and excluded in such scenarios: FH-deficient RCC, high-grade urothelial carcinoma of renal pelvis, renal medullary carcinoma, and metastatic carcinoma from another organ." (PMID 31905821, 2019). "Molecular genetic testing should be considered after excluding other entities in the differential diagnosis (i.e., FH-deficient RCC, renal medullary carcinoma)." (PMID 31905821, 2019). "The remaining IHC profile of ALK‐rearranged RCC is variable, but includes reactivity for PAX8 and vimentin, and retained FH and INI1, the last two being useful in differentiating it from FH‐deficient RCC and SMARCB1‐deficient renal medullary carcinoma, respectively." (PMID 41384711, 2026).
atypical hemolytic-uremic syndrome (7 papers, 2013 to 2025). A rare, genetic thrombotic microangiopathy due to dysregulation of the alternative complement pathway and characterized by the triad of hemolytic anemia, thrombocytopenia, and acute renal dysfunction. "In atypical hemolytic uremic syndrome (aHUS), complement overactivation on endothelial surfaces, oftentimes caused by FH mutations, promotes thrombotic microangiopathy and consequently hemolytic anemia, thrombocytopenia, and acute and chronic renal failure." (PMID 40338657, 2025). "In humans, FH deficiency is the main cause of atypical hemolytic uremic syndrome as well as kidney and eye diseases." (PMID 38698856, 2024). "Complement factor H (fH) is a plasma protein that regulates activation of the alternative pathway, and mutations in fH are associated with a rare form of thrombotic microangiopathy (TMA), known as atypical hemolytic uremic syndrome (aHUS)." (PMID 23991205, 2013).
von Hippel-Lindau disease (7 papers, 2005 to 2024). An autosomal dominant disorder caused by pathogenic variants in the VHL gene, leading to an increased risk of various benign and malignant tumors, including hemangioblastomas, retinal hemangiomas, endolymphatic sac tumors, renal cell carcinoma, and pheochromocytomas. "HIF-1α protein stabilization can also be seen in the development of multiple neoplasms in patients with von Hippel-Lindau disease or mutations in several enzymes of the tricarboxylic acid (TCA) cycle, such as succinate dehydrogenase (SDH) and fumarate hydratase (FH)." (PMID 20844768, 2010).
colorectal cancer (6 papers, 2016 to 2025). A primary or metastatic malignant neoplasm that affects the colon or rectum. "Fumarate accumulates significantly in colorectal cancers harboring fumarate hydratase (FH) mutations, while in sporadic CRC, it also accumulates due to TCA cycle blockage." (PMID 41488637, 2025). "Furthermore, FH is downregulated in sporadic clear cell carcinomas and colorectal cancer, and some evidence supports the role of FH mutations in breast, bladder, and testicular cancers." (PMID 37689804, 2023). "Strikingly, we found that FH expression was significantly upregulated in human and murine colorectal cancer cells by RBM15 KO, which in turn led to a reduction in fumarate levels." (PMID 40370450, 2025). "Collectively, these findings suggest that RBM15 depletion significantly affects carbon metabolism and upregulates the expression level of FH, which in turn downregulates fumarate in colorectal cancer." (PMID 40370450, 2025).
hereditary cancer syndromes (6 papers, 2021 to 2026). "Hereditary leiomyomatosis and renal cell carcinoma (HLRCC) is a rare, aggressive hereditary cancer syndrome caused by germline mutations in the fumarate hydratase (FH) gene." (PMID 42266714, 2026). "Germline mutations in the genes encoding succinate dehydrogenase (SDH) and fumarate hydratase (FH) are implicated in hereditary cancer syndromes." (PMID 39438765, 2024). "Both SDH-deficient and FH-deficient RCCs are associated with a poor prognosis and warrant germline analysis to identify patients with hereditary cancer syndromes." (PMID 34822422, 2021). "In addition, inactivating mutations in nuclear genes whose protein products function in mitochondria occur in several hereditary cancer syndromes, including those caused by mutations in fumarate hydratase (FH) and succinate dehydrogenase (SDH)." (PMID 37971875, 2023).
nasopharyngeal carcinoma (6 papers, 2016 to 2022). A carcinoma arising from the nasopharyngeal epithelium. "For example, HELLS can promote the progression of nasopharyngeal carcinoma by regulating fumarate hydratase expression." (PMID 35774795, 2022). "It has been recently reported that in nasopharyngeal carcinoma, the chromatin remodeling factor lymphoid-specific helicase binds the FH promoter and recruits the epigenetic silencer factor G9a to inhibit the transcription of FH." (PMID 28352611, 2017). "Similarly, silencing FH increased the clonogenicity and enhanced the migratory and invasive potentials of nasopharyngeal cancer cells." (PMID 35083212, 2021). "A recent study demonstrated the relationship between FH and EMT in nasopharyngeal carcinoma (NPC)." (PMID 31822964, 2020).
smooth muscle tumor (6 papers, 2002 to 2026). A benign or malignant myomatous neoplasm arising from smooth muscle. "Overall, we found a similar pattern of epigenetic deregulation in FH-deficient smooth muscle tumors and SDH-deficient PGL/PCC, with loss of 5hmC proving a robust marker of deregulated DNA methylation." (PMID 26472283, 2015). "In contrast, FH-deficient smooth muscle tumors showed nuclear exclusion of TET1 in only 40% of cases and exclusion was not correlated with loss of 5hmC." (PMID 26472283, 2015). "We also show for the first time that FH-deficient smooth muscle tumors exhibit increased H3K9me3 methylation compared to wildtype tumors." (PMID 26472283, 2015). "Despite small numbers, our results showed significantly elevated H3K9me3 levels in FH-deficient smooth muscle tumors, supporting the hypothesis that fumarate inhibits histone demethylation." (PMID 26472283, 2015). "Moreover, FH-deficient smooth muscle tumors (83%) showed loss of 5hmC expression in tumor cells as compared to normal smooth muscle or FH wildtype smooth muscle tumors." (PMID 26472283, 2015). "Interestingly, we found a similar pattern of epigenetic deregulation in FH-deficient smooth muscle tumors compared to SDH-deficient PGL/PCC, both in terms of loss of 5hmC expression and increased trimethylation of H3K9 in tumor cells." (PMID 26472283, 2015). "Interestingly, FH-deficient smooth muscle tumors showed significantly elevated levels of H3K9me3 compared to smooth muscle cells (p = 0.027) and FH wildtype tumors (p = 0.004)." (PMID 26472283, 2015). "To estimate the prevalence of FH mutations in smooth muscle tumors and to exclude FH mutations in SDH wildtype PGL, we performed immunohistochemistry for 2-succinocysteine (2SC), a robust biomarker for FH mutations." (PMID 26472283, 2015). "Of all hereditary and sporadic smooth muscle tumors (n = 56), 1 uterine LM and 1 cutaneous LM from a patient with suspected HLRCC, and 2 LMS tumors were positive for 2SC, indicating the presence of an FH mutation." (PMID 26472283, 2015). "Absence of nuclear staining was also more frequent in FH-deficient smooth muscle tumors (2 of 5, 40%), compared to FH wildtype tumors (9/45, 20%) or smooth muscle tissue (0/8)." (PMID 26472283, 2015). "To date, DNA and histone methylation profiles have not been reported for FH-deficient smooth muscle tumors." (PMID 26472283, 2015). "Given that that oxidation of 5mC to 5hmC is considered to be a nuclear event, these results suggests TET1 is not the main player in the hydroxylation of 5mC in FH-deficient smooth muscle tumors." (PMID 26472283, 2015). "Using immunohistochemistry, we investigated the distribution of 5mC, 5hmC, TET1, and histone methylation in SDH- mutant PGL/PCC and in FH-deficient smooth muscle tumors in comparison to non-SDH or FH-mutated PGL/PCC and smooth muscle tumors, respectively." (PMID 26472283, 2015). "Although mutations in FH do not appear to be involved in the development of sporadic smooth muscle tumours it is conceivable that other mitochondrial defects may be involved." (PMID 12177782, 2002).
atherosclerosis (5 papers, 2021 to 2025). A disease characterized by the build-up of fatty material and calcium deposition in the arterial wall resulting in partial or complete occlusion of the arterial lumen. "Incorporating information on FH mutations into risk assessment for atherosclerosis patients can help predict disease progression and cardiovascular outcomes more effectively." (PMID 40510188, 2025). "Moreover, multivariate logistic regression analysis showed that FH mutation beyond cholesterol levels was an independent risk factor of higher results of atherosclerosis parameters." (PMID 37685656, 2023). "We sought to determine whether the FH mutation was connected to higher CMR atherosclerosis parameters." (PMID 37685656, 2023). "We speculated that the long-term LDL exposure of FH variant carriers may result in a deleterious impact on the development of atherosclerosis." (PMID 34573395, 2021). "Therefore, FH variant carriers with lifelong excess LDL-C accumulated in their arteries produce atheromas, leading to accelerated atherosclerosis and CVD development." (PMID 34573395, 2021). "Considering that max IMT is one of indices of atherosclerosis, both ALDOA-Abs and FH-Abs could reflect the degree of atherosclerosis." (PMID 34243715, 2021). "Atherosclerosis is a multifactorial disease, and the upstream atherosclerosis-inducing mechanism via hyperlipidemia could be different from that via hypertension, of which the latter pathway might be accompanied with the elevated expression of ALDOA and FH." (PMID 34243715, 2021).
collecting duct carcinoma (5 papers, 2020 to 2025). "In the rare RCC category, collecting duct carcinoma (CDC) harbors mutations in NF2, SETD2, SMARCB1, FH, and CDKN2A genes while renal medullary carcinoma is distinctively characterized by loss of SMARCB1/INI1 tumor suppressor protein." (PMID 32575429, 2020).
Hypertension (5 papers, 2020 to 2024). The presence of chronic increased pressure in the systemic arterial system. "HeFH patients free of cardiovascular events were younger and mostly female, and a small percentage presented comorbidities (such as T2DM, and hypertension) and a confirmed positive genetic mutation in canonical FH genes." (PMID 38732050, 2024). "The predictive values of ALDOA-Abs and FH-Abs for TIA were similar to that of hypertension, which is a typical risk factor of TIA." (PMID 34243715, 2021). "In a correlation analysis, both ALDOA-Abs and FH-Abs were well associated with hypertension, coronary heart disease, and habitual smoking." (PMID 34243715, 2021).
Obesity (5 papers, 2022 to 2025). Accumulation of substantial excess body fat. "It has been observed that miR-144 suppresses Nrf2 activity in obesity by modulating the TCA cycle enzyme fumarate hydratase (FH), which reduces fumarate availability and impairs antioxidant defences." (PMID 39940866, 2025). "Conversely, increased FH activity impairs the antioxidant response in obesity." (PMID 38517358, 2024).
coronary artery disease (4 papers, 2020 to 2021). "Coronary artery disease was the most frequent ASCVD in DLCN ≥ 6 with FH mutation." (PMID 33668494, 2021). "Studies have shown that coronary artery disease risk is higher in carrier of FH mutations compared to those without, this is likely the consequence of a higher life-long exposure to LDL." (PMID 32040480, 2020).
diabetes (4 papers, 2017 to 2020). "Mice in which fumarate hydratase deletion causes progressive diabetes show a similar impairment of mitochondrial metabolism and ATP production." (PMID 31171772, 2019). "Diabetic rats had an increased blood glucose level, urinary output, and venous FH activity following induction of diabetes, as well as lower plasma and urinary creatinine (Cr) levels." (PMID 32541797, 2020). "have shown that progressive diabetes develops if fumarate hydratase is deleted in mouse pancreatic β cells." (PMID 28954230, 2017). "Moreover, novel HO-1 inhibition tools were reported such as arylethanolimidazole derivatives in cancer, caffeic acid phenethyl ester in diabetes and fumarate hydratase as target genes in cancer." (PMID 32485912, 2020). "We show here that lack of the Krebs-cycle enzyme FH causes a progressive deterioration of β cell function, resulting in severe diabetes associated with impaired oxidative metabolism, ATP production, intracellular calcium handling, and cytosolic acidification." (PMID 28954230, 2017).
diabetic kidney disease (4 papers, 2016 to 2022). Progressive kidney disorder caused by vascular damage to the glomerular capillaries, in patients with diabetes mellitus. "In addition, Nox4 plays a key role in the pathogenesis of diabetic nephropathy by targeting renal fumarate hydratase, the enzyme that increases fumarate levels." (PMID 27649164, 2016).